BDNF (brain derived neurotrophic factor)
Diseases named in the same sentence as BDNF in open-access papers (continued):
Sharing a sentence is not in itself a finding about the gene and the disease.
Stroke (continued). "Further studies in humans post-stroke are needed to identify the most appropriate protocol of treatment to increase BDNF concentration and its correlation with motor recovery." (PMID 30210424, 2018). "One of the best understood trophic factors in the context of stroke is BDNF, which promotes neurological recovery following middle cerebral artery occlusion." (PMID 30405724, 2018). "That study suggested that brain-derived neurotrophic factor (BDNF)/tropomyosin receptor kinase B (TrKB) pathways seemed to be involved in niacin-induced neuroprotective effects after a stroke." (PMID 29565276, 2018). "In this preliminary study, we aimed to investigate the potential of BDNF as a biomarker in stroke rehabilitation by analyzing the relationship between serum BDNF and depressive mood in subacute stroke patients." (PMID 30322026, 2018). "Direct infusion or cell-based gene therapy to overexpress recombinant BDNF in stroke and spinal cord injury, significantly increased OPC numbers and expression of myelin proteins MBP, MOG and PLP." (PMID 30572673, 2018). "Collectively, these studies indicate that BDNF plays a key role in the neuro-reparative processes that mediate cortical connectivity and promote recovery of function post-stroke." (PMID 30486515, 2018). "A number of studies have also shown that the use of BDNF can stimulate neurogenesis and the migration of neuronal progenitors from the subventricular zone to the site of stroke." (PMID 30081596, 2018). "Generally, this review shows that aerobic exercise is able to promote changes in central BDNF concentrations in animal models of stroke." (PMID 30210424, 2018). "Collectively, these data indicate that intracerebral BDNF therapy can improve functional recovery, although its efficacy is dependent on both dose and time allowed for recovery following stroke." (PMID 30486515, 2018). "Methodological characteristics and main results of studies that evaluated the effects of physical activity on the BDNF levels post-stroke." (PMID 30210424, 2018). "Mature BDNF has a pronounced protective and neurotrophic effect, and brain mature BDNF has been shown to increase after stroke." (PMID 30322026, 2018). "Mesenchymal cells engineered to produce VEGF, BDNF, and placental growth factor were used for stroke treatment in a rat model." (PMID 29497380, 2018). "The current review illustrates the consistencies and discrepancies in the literature regarding the response of BDNF concentrations following physical exercise training in subjects post-stroke or animals submitted to experimental CNS injury." (PMID 30210424, 2018). "Although various molecular signaling pathways are engaged in neural plasticity and recovery after stroke, BDNF signaling has emerged as a key player in these processes." (PMID 29997355, 2018). "They evaluated functional recovery and serum BDNF level in post-stroke patients and the relationship between the two." (PMID 30319398, 2018). "Still, hydrogel + BDNFHIGH treatment reduced astrogliosis and infarct volume, possibly by mitigating glial-scar formation, highlighting the therapeutic potential of BDNF-infused hydrogels for the treatment of stroke-related pathology." (PMID 30486515, 2018). "The brain-derived neurotrophic factor (BDNF), as a regulator of neuronal survival and neurogenesis, is believed to be involved in the protection and recovery of functions after stroke." (PMID 30410555, 2018). "Brain derived neurotrophic factor (BDNF) can be used post stroke or brain injury to provide neuroprotection and prevent neuronal death." (PMID 29843371, 2018). "Recent studies have highlighted BDNF as an important neurotrophic factor involved in motor learning, recovery and neural rehabilitation after a stroke." (PMID 30210424, 2018). "BDNF plays a crucial role in neuronal survival and plasticity, and its importance for stroke recovery has been demonstrated in Kurozumi's study." (PMID 30405724, 2018).
Stroke (continued). "Previous reports have demonstrated that exercise, environment enrichment, and neuronal pharmacotherapy after stroke mediate neuroplastic changes through the expression of BDNF in the contralateral and ipsilateral hemispheres." (PMID 29997355, 2018). "According to these reports, BDNF has emerged as a key facilitator of neuroplasticity for motor learning and rehabilitation in stroke." (PMID 30322026, 2018). "Only one study evaluated human BDNF concentrations following physical exercise, while 20 studies were experimental studies using a stroke model in animals." (PMID 30210424, 2018). "This is exciting as it suggests targeting BDNF signalling is a viable therapeutic strategy for neurologic conditions such as MS, stroke and traumatic injury where myelin damage is the prominent underlying cause of clinical dysfunction." (PMID 30572673, 2018). "In stroke patients, serum BDNF levels at the acute phase showed a strong relationship with the development of PSD within 3 months after onset." (PMID 30322026, 2018). "BDNF contributes to the promotion of angiogenesis, brain plasticity and enhanced functional recovery after stroke." (PMID 28212538, 2017). "Results suggested that NAM enhanced the expression of BDNF after stroke, which correlates with enhanced recovery of myelination." (PMID 28656112, 2017). "Accordingly, in this investigation, the focus was the ability of candesartan to upregulate BDNF expression in hypertensive animals after stroke and to assess eNOS involvement in this proposed effect." (PMID 28640888, 2017). "Enhancement of BDNF production after stroke, mainly attributable to perilesional neurons but also to microglia, has been suggested as a brain compensatory mechanism to prevent excessive neuronal death." (PMID 28134845, 2017). "Brain-derived neurotrophic factor (BDNF) has been demonstrated to play a role in both protection and recovery of functions after stroke." (PMID 28373887, 2017). "The enhancement of BDNF seems to be related to improvements in stroke recovery, even in animal models, which show how social interactions are fundamental in the poststroke recovery." (PMID 28373915, 2017). "This amelioration was demonstrated to be eNOS-mediated and is consistent with BDNF expression after stroke." (PMID 28640888, 2017). "In conclusion, our findings demonstrated the ability of candesartan to confer protection after stroke and increase mature BDNF expression in both hemispheres of hypertensive animals in an eNOS-dependent manner." (PMID 28640888, 2017). "Several clinical trials focused in the elderly and patients of stroke and neurodegenerative diseases, have reported the induction by exercise of a cognitive improvement together with an increase in BDNF levels." (PMID 28134845, 2017). "Combined ampakine and local delivery of BDNF improved post‐stroke functional recovery in aged mice by activating Akt/CREB signalling." (PMID 28098423, 2017). "Our previous results suggested that the beneficial effects of CLS involve the activation of CREB/BDNF signaling in post-stroke depression." (PMID 28208711, 2017). "So, even in situations of compromised BBB integrity such as stroke, BDNF nanoparticles are still more efficient than native BDNF improving neuropathological and neurobehavioral outcomes." (PMID 28134845, 2017). "Combined treatments with Ampakine and brain-derived neurotrophic factor (BDNF) enhance post stroke functional recovery in aged mice via Akt-CREB signaling." (PMID 29254199, 2017). "Salvianolate lyophilized injection (10.5, 21, and 42 mg/kg) ameliorated the deficits observed in diabetic rats after stroke normalizing the protein level of the mature form of BDNF." (PMID 29464125, 2017). "Still, in rat models, neurotrophin-4 increases its serum levels after a stroke event and exhibits the same properties of BDNF, as it is likewise a ligand of trkB." (PMID 28373915, 2017).
Stroke (continued). "The most likely explanation for this outcome is the incapacity of BDNF to trigger appropriate neurotrophic signalling after stroke due to a pathological imbalance of TrkB receptor isoforms." (PMID 28134845, 2017). "Physical exercise should ameliorate this circumstance, even by increasing the hippocampal level of BDNF in the early stages of a stroke (cerebral embolism)." (PMID 28373915, 2017). "Increased BDNF levels facilitated enhanced recovery of myelination after stroke via activation of TrkB receptor." (PMID 28656112, 2017). "BDNF is a member of the neurotrophin family, which has recently been shown to play a role both in protection and in recovery of function after stroke." (PMID 28230741, 2017). "With immunohistochemistry, it has been shown that human MSCs can produce BDNF after their transplantation into a rat model of stroke." (PMID 26607630, 2016). "There was a significant interaction [F: P = 0.0423] between housing conditions and stroke in BDNF expression, with significantly higher BDNF expression in ST-PH (P < 0.01 t-test between ST-PH vs. STISO) compared to ST-ISO mice." (PMID 27125783, 2016). "One candidate protein in this setting is Nogo-A, which has been shown to worsen stroke outcome and to antagonize the effects of BDNF in neurons." (PMID 27127602, 2016). "This is further supported by recent work that shows that BDNF also improves functional outcome after stroke by mediating axonal growth, OPC proliferation, oligodendrocyte differentiation, remyelination, and fiber tract connectivity." (PMID 27125783, 2016). "Consistently, rt-PA administration induces an increase in brain BDNF levels and BDNF can cross the blood brain barrier from the brain to the blood especially since rt-PA has been shown to exacerbate stroke-induced blood brain barrier disruption." (PMID 26469350, 2015). "Surprisingly, there is a lack of studies specifically designed to investigate the impact of t-PA treatment on circulating BDNF levels in stroke." (PMID 26469350, 2015). "Intranasal administration of BDNF-overexpressing mesenchymal cells three days after stroke in neonatal rats results in reduced gray and white matter loss as well as improved motor functions at 14 days after stroke." (PMID 25942688, 2015). "Serum BDNF levels in stroke patients with a systolic blood pressure lower or higher than 160 mmHg at the admission." (PMID 26469350, 2015). "After stroke, it has also been shown that TrkB-expressing astrocytes bind and sequester vasculature-derived BDNF to promote neural precursor cell migration from the subventricular zone to the ischemic areas." (PMID 25942688, 2015). "Infusion of a variety of neurotrophic growth factors, including basic fibroblast growth factor, epidermal growth factor and brain-derived neurotrophic factor, into the lateral ventricle of the rodent with stroke increases neurogenesis." (PMID 25867181, 2015). "In light of this result, it would have been tempting to consider post-stroke serum BDNF as a biomarker of stroke recovery." (PMID 26469350, 2015). "Correlations between NIHSS score variations over periods ranging from D0 to D1, D0 to D7 and D0 to D90 and serum BDNF levels in stroke patients at D0, D1, and D7." (PMID 26469350, 2015). "Recently, t-PA has been linked to the metabolism of brain-derived neurotrophic factor (BDNF), a major neurotrophin involved in post-stroke neuroplasticity." (PMID 26469350, 2015). "In a photothrombotic stroke model, daily intravenous injections of BDNF for five days following stroke improves sensorimotor outcomes assessed by rotorod, balance beam, and adhesive removal tests." (PMID 25942688, 2015). "Implantation of BDNF-transfected fibroblasts into the somatosensory cortex after stroke results in upregulation of TrkB receptors in cortical neurons of the penumbra and increased neuron survival in the cortex." (PMID 25942688, 2015).
Stroke (continued). "Serum BDNF levels were measured before and after (1h, 4h and 24h) the induction of stroke in rats treated with rt-PA or vehicle." (PMID 26469350, 2015). "Infusion of galectin-1, an endogenous mammalian lectin, enhanced the expression and secretion of astrocytic BDNF, reduced the number of apoptotic neurons at the ischemic boundary, and improved functional recovery after experimental stroke." (PMID 24818146, 2014). "Daily intravenous bolus applications of BDNF after stroke resulted in significantly improved sensorimotor scores 6 weeks after stoke as well as enhanced neurogenesis in the DG and SVZ." (PMID 24818146, 2014). "Intravenous infusion of BDNF has been shown to reduce infarct volume as early as 5 hours after stroke." (PMID 24690461, 2014). "These cells secrete various growth factors like VEGF, bFGF, and BDNF which promote functional outcome after stroke." (PMID 25126443, 2014). "BDNF genotype frequency distribution and association to recovery as measured by the change in NIHSS score from acute stroke to 3 months post-stroke (ΔNIHSS)." (PMID 25470006, 2014). "Physical training for stroke rat models was reported to facilitate motor function recovery and upregulate BDNF levels." (PMID 25045713, 2014). "Numerous studies have demonstrated that neurotrophins, particularly BDNF, reduce infarct volume in rodents when administered before, during, and/or after experimental stroke." (PMID 24818146, 2014). "BDNF is related to neuroplasticity contributing to motor learning, recovery, and neural rehabilitation after stroke." (PMID 25045713, 2014). "Niacin also increased BDNF and TrkB expression in neurons and reduced infarct volume in vivo following experimental stroke." (PMID 24818146, 2014). "In contrast, neurotrophins such as BDNF are highly up-regulated in the growth-permissive penumbra und repressed in the stroke core." (PMID 25018717, 2014). "Overexpression of growth factor genes including VEGF, GDNF, BDNF, and Akt1 was able to significantly promote the survival of NSCs in stroke animal model." (PMID 24719869, 2014). "Further, the increased mRNA expression of rat-specific BDNF seen in sham versus PBS animals implies a reduction in the BDNF endogenous levels after stroke." (PMID 24690461, 2014). "As far as we are aware, only one study has evaluated both short-term (after 2-weeks) and long-term (after 1 year) consequences after stroke for BDNF genotypes." (PMID 25470006, 2014). "The local intracerebral grafting of adult mouse NPCs in the brain parenchyma is associated with elevated brain concentrations of BDNF, FGF, and VEGF in the subacute stroke phase, i.e., at 4 days after MCAO in mice." (PMID 25278840, 2014). "BDNF has been used to treat photothrombotic stroke rats and it improved motor function recovery when compared to spontaneous recovery." (PMID 25045713, 2014). "Early physical training facilitates rehabilitation after stroke, but it is also a source of stress that mediates BDNF regulation." (PMID 25045713, 2014). "Other studies also show that higher BDNF level in the brain indicates better motor function recovery after stroke." (PMID 25045713, 2014). "At 2 weeks after stroke, rat BDNF mRNA expression was significantly higher in the ipsilateral hemisphere of the sham group compared with the PBS (P < 0.0001), cbMNC (P < 0.01), and cb/cmMSC (P < 0.001) groups." (PMID 24690461, 2014). "It is tempting to suggest that, when given as a pre-treatment, C21 prevented the detrimental polarising effects of stroke by enhancing the actions of the AT2R-positive-BDNF-producing microglia." (PMID 24752645, 2014). "BDNF promotes both neuro- and angiogenesis and has been shown to promote post-stroke recovery in animal models." (PMID 25470006, 2014). "BDNF genotype percentages by stroke outcome status as measured by the modified Rankin Scale (mRS) at 3 months, 2 years and 7 years post stroke." (PMID 25470006, 2014).
Stroke (continued). "Several animal studies have shown that BDNF levels are increased in the brain after stroke and one study showed that plasma BDNF levels were positively correlated with stroke severity in rats." (PMID 25470006, 2014). "In light of these data it seems arguable that apoptotic MNC-secretomes provide, at least in part, indirect protection in this experimental stroke model via BDNF." (PMID 25383184, 2014). "Although relatively large compared to other studies on BDNF genotypes and post-stroke outcome, the sample size is small by genetic study standards and thus the statistical power is low, which is especially true for the 7-year follow-up." (PMID 25470006, 2014). "Transplantation of umbilical cord blood-derived stem cells in animal models of stroke demonstrates functional recovery, reducing infarct size, and higher expression of neuroprotective factors, such as BDNF and VEGF." (PMID 24147217, 2013). "Stroke triggers the expression of BDNF in affected areas, and intravenous or intraventricular BDNF administration in animals subjected to phototrombotic ischemia leads to an increased number of SVZ-derived cells in injured tissues." (PMID 23383048, 2013). "Intraventricular infusion of BDNF antisense oligonucleotides blocked the expression of BDNF mRNA and attenuated skilled reaching recovery after stroke." (PMID 24312581, 2013). "The results showed that exercise post-stroke significantly increased the expression of BDNF, VEGF and synapsin in cortical and striatal tissues." (PMID 24260348, 2013). "Our new data in concert the other reports, indicate that eNOS plays an important role in regulating endogenous BDNF and TrkB, which are involved in axon growth and synaptic function, and thereby in functional recovery after stroke." (PMID 24236179, 2013). "Transplantation of umbilical cord blood-derived stem cells in animal models of stroke has produced encouraging results of functional recovery, reducing infarct size, and higher expression of neuroprotective factors, such as BDNF and VEGF." (PMID 25177494, 2013). "For example, systemic administration of BDNF enhanced recruitment of NPCs into the ipsilateral striatum after stroke." (PMID 24312581, 2013). "The purpose of this study was to identify the role of BDNF in SVZ cells using AAV-BDNF in an animal model of stroke." (PMID 24312581, 2013). "Studies performed on stroke, in either mice or humans, have indicated that the release of BDNF has been altered." (PMID 24300402, 2013). "For example, intravenous administration of BDNF stimulated recruitment of NPCs migrate to the lesioned striatum after stroke." (PMID 24312581, 2013). "A recent report indicated that activation of AMPA receptors post-stroke enhances behavioral recovery through BDNF signaling in stroke mice." (PMID 24312581, 2013). "Experimental data has supported the idea that brain derived neurotrophic factor (BDNF) has beneficial effects in animal models of stroke." (PMID 24312581, 2013). "We studied the expression of BDNF and its receptors in the post-stroke striatum and explored BDNF involvement in the mechanisms of vasculature-mediated migration of neuronal precursors." (PMID 23383048, 2013). "Stroke induces an increase in mature BDNF expression which coincides with the increase of synaptophysin both in ipsilateral cortex and hippocampal territories." (PMID 24236179, 2013). "Consistent with a rapid induction of the transcription of BDNF gene in response to stroke, increased BDNF mRNA and proteins (ELISA tests) were observed in the first 24h after stroke onset as compared to preischemic values." (PMID 22962604, 2012). "In this region, exercise resulted in a comparable increase in the production of mature BDNF in intact and stroke rats but increased proBDNF levels only in intact rats." (PMID 22962604, 2012). "Multiple regression analyses of BDNF genotype and promoter methylation on poor stroke outcomes at 2 weeks and at 1 year." (PMID 23240009, 2012).